LEP (leptin)
Diseases named in the same sentence as LEP in open-access papers (continued):
Sharing a sentence is not in itself a finding about the gene and the disease.
breast cancer (continued). "Egyptian patients with breast cancer frequently present the AA genotype of LEP G2548A compared to healthy women, while the LEPR Q223R polymorphism is associated with the development of breast cancer." (PMID 30404206, 2018). "In breast cancer cells, Notch signaling is necessary for leptin-induced expression of VEGF and VEGFR2 (as detailed above) suggesting that Notch is a downstream mediator of leptin-mediated regulation of breast cancer cell growth and tumor angiogenesis." (PMID 30154786, 2018). "Our team’s previous work showed that leptin induced an inflammatory response in breast cancer in mice, and a different proliferative effect on neoplastic cells." (PMID 30563501, 2018). "Chen and colleagues found that breast cancer patients had higher serum leptin concentration but lower serum adiponectin concentration, thus leading to a significant higher L/A ratio than control group." (PMID 30013512, 2018). "In obese patients, increased secretion of hormones such as leptin, as well as adipokines, contribute to the development of breast cancer." (PMID 29804217, 2018). "In breast cancer, low dosage addition of leptin (0.625 nM) significantly induced breast cancer cell growth via increased cell cycle transition." (PMID 29682217, 2018). "In healthy individuals with normal weight, the concentration of leptin in the bloodstream is about 5–20 ng/mL, while, in a patient with breast cancer, the leptin levels reach up to 100 ng/mL." (PMID 30404206, 2018). "Another study, which explored the relationship between leptin and adiponectin in breast cancer patients, is consistent with this assumption." (PMID 30013512, 2018). "Further studies are therefore needed to better understand the precise role played by adipose tumor microenvironment and by adipokines such as IL-6, leptin and TNFα in breast cancer progression." (PMID 29389973, 2018). "Collectively, these studies indicate that leptin-induced ER-α-positive breast cancer cell viability is mediated via suppressing CCN5 expression." (PMID 29370782, 2018). "In this study, we also confirmed that leptin levels were significantly related to the occurrence of breast cancer, which is consistent with previous studies." (PMID 29088874, 2017). "Recently, protective effects of natural compounds, honokiol and benzyl isothiocyanate, in leptin-stimulated breast cancer cells have been demonstrated in vitro." (PMID 28930270, 2017). "Herein, we investigated mechanisms for estrogen receptor signaling-mediated growth of breast cancer cells, particularly focusing on autophagy, which plays a crucial role in leptin-induced tumor growth." (PMID 29312618, 2017). "We have previously shown that leptin induces the expression of Notch receptors and ligands in breast cancer." (PMID 27999190, 2017). "Decreased concentrations of adiponectin, and increased concentrations of leptin, IL-6, IL-8, TNF-α, resistin and visfatin were significantly associated with risk of breast cancer." (PMID 29088874, 2017). "This study provides experimental evidence of quercetin, curcumin and EGCG as potential dietary compounds which can inhibit leptin-induced MCF-7 breast cancer cell proliferation." (PMID 28930270, 2017). "Indistinctly of the molecular classification of breast cancer of the cell lines used, they all express leptin, adiponectin, AdipoR1, and AdipoR2." (PMID 29311755, 2017). "Evidence from several in vitro studies shows a proliferative effect of leptin on cancer cells including MCF-7 breast cancer cells." (PMID 28930270, 2017). "It has been reported that the ERK1/2 pathways play a major role in leptin signaling in MCF-7 breast cancer cells." (PMID 28930270, 2017). "Although over twenty adipokines are known; only twelve (adiponectin, leptin, IL-6, TNF-α, HGF, PAI–1, resistin, secreted frizzled-related protein 5 (SFRP-5), lipocalin 2, IL-8, apelin and visfatin) have been implicated in breast cancer." (PMID 29088874, 2017).
breast cancer (continued). "In this study, we have also showed that leptin can increase the survival of MCF-7 breast cancer cells in a significant dose-dependent manner after 48 h incubation." (PMID 28930270, 2017). "Here, we treated suberoylanilide hydroxamic acid (SAHA) on Leptin-induced cell proliferation and invasion in the estrogen-receptor-positive breast cancer cell line MCF-7 and triple-negative breast cancer cell line MDA-MB-231." (PMID 27926517, 2017). "Several researchers have also demonstrated reduced leptin and leptin receptor gene expression in breast cancer cell lines after treatment with curcumin." (PMID 28930270, 2017). "In conclusion, the results from both in vitro and in vivo models clearly demonstrated that ER signaling plays a crucial role in leptin-induced growth of breast cancer cells via autophagy induction." (PMID 29312618, 2017). "Collectively, these results indicate that ER signaling plays a critical role in autophagy induction by leptin in breast cancer cells." (PMID 29312618, 2017). "Meanwhile, we evaluated the changes of histone acetylation levels in breast cancer cells with Leptin and SAHA treatment." (PMID 27926517, 2017). "The development of breast cancer is influenced by the adipose tissue through the proteins leptin and adiponectin." (PMID 29311755, 2017). "Would healing assay indicated that Leptin stimulated cell invasion in both cell lines, implying that Leptin induced breast cancer cell growth through autocrine and paracrine pathways." (PMID 27926517, 2017). "One more interesting information coming from our study concerns Leptin; Leptin serum levels seem directly and independently from other factors related to the presence of breast cancer." (PMID 29254161, 2017). "Here, we evaluated SAHA on Leptin-induced cell proliferation and invasion in the breast cancer cell line MCF-7 and MDA-MB-231." (PMID 27926517, 2017). "The mutagenic effect of leptin has been observed in various cell types, including breast cancer, endometrial cancer and prostate cancer cells." (PMID 28861689, 2017). "Herein, we have demonstrated for the first time that ER signaling plays a critical role in leptin-induced autophagy induction in breast cancer cells, which in turn leads to both inhibition of apoptosis and acceleration of cell cycle progression." (PMID 29312618, 2017). "A number of investigations were launched to identify the mechanisms which link leptin with tumor growth and progression of breast cancer." (PMID 29121911, 2017). "It was previously reported that leptin signaling induced a complex molecular crosstalk in breast cancer that involved Notch and IL-1 signaling (NILCO)." (PMID 28659656, 2017). "In group 1 of the MCF-7 breast cancer cells, it was observed that the effect of leptin over cell proliferation was antiproliferative, decreasing up to 64.71%." (PMID 29311755, 2017). "Jak/STAT3, ERK1/2, phosphoinositide 3-kinase pathways and cyclin D1 expression pathways are reported to be involved in mediating leptin-stimulated breast cancer cell growth." (PMID 28930270, 2017). "Considering that autophagy induction plays a critical role in leptin-induced tumor growth, we next investigated the role of ER signaling in leptin-induced autophagy activation in breast cancer cells." (PMID 29312618, 2017). "To evaluate how Leptin and SAHA influence morphological features associated with breast cancer cell proliferation, we measured cell invasiveness by wound healing assay." (PMID 27926517, 2017). "Cancer associated adipocytes are the source of a number of secreted factors including leptin, IL6, IL1β and estrogen, and these factors have been independently linked with breast cancer progression." (PMID 28542577, 2017). "Another adipocyte-secreted factor, leptin, was shown to promote breast cancer cell migration and invasion via IL-18 expression and secretion." (PMID 28915700, 2017).
breast cancer (continued). "In leptin-stimulated breast cancer cells, STAT3, extracellular signal-regulated kinase (ERK), and Akt activation has been demonstrated in several in vitro studies." (PMID 28930270, 2017). "Herein, we have also shown that leptin induces AMPK phosphorylation in breast cancer cells through ER-dependent mechanism." (PMID 29312618, 2017). "Several studies have shown that leptin can exert proliferative effects on breast cancer cells in vitro." (PMID 28930270, 2017). "It has been shown that Aca1, Allo-aca and D-ser can inhibit leptin-stimulated proliferation in MCF-7 breast cancer cells." (PMID 28861689, 2017). "Leptin exerts biological effects by binding to its corresponding receptors (Ob-Rs), and previous studies confirmed that Leptin is over-expressed in breast cancers." (PMID 27926517, 2017). "The detailed mechanisms underlying differential roles of estrogen receptor signaling in leptin-induced tumor growth between MCF-7 breast cancer cells and HepG2 hepatic cancer cells remains to be delineated." (PMID 29312618, 2017). "Some studies indicated that the serum LEP level was significantly higher in breast cancer patients compared with which in controls both pre-menopausal and post-menopausal." (PMID 29312594, 2017). "Over-expression of leptin has been found to promote the proliferation, migration and angiogenesis of breast cancer cell, thereby accelerating the growth and metastasis of breast cancer." (PMID 28415788, 2017). "Taken together, these findings clearly demonstrate that autophagy targets and degrades E2F1, thereby leading to cyclin D1 induction in leptin-treated MCF-7 breast cancer cells." (PMID 29312618, 2017). "Effects of the compounds, found to be protective (quercetin, curcumin and EGCG) against leptin-induced breast cancer cells, on phosphorylation of ERK1/2 was assessed in the present study." (PMID 28930270, 2017). "Taken together, these results suggest that ER signaling plays an important role in leptin-induced suppression of Bax expression probably via autophagy induction in breast cancer cells." (PMID 29312618, 2017). "We previously reported that leptin induces the expression and activation of Notch in breast cancer cells." (PMID 27999190, 2017). "Results from the present study indicate that suppression of ER signaling and autophagy induction would be a novel strategy that can be used to suppress leptin-induced growth of breast cancer." (PMID 29312618, 2017). "Taken together, these results demonstrate that estrogen receptor signaling plays a key role in leptin-induced growth of breast cancer cells via autophagy activation." (PMID 29312618, 2017). "We have previously found that leptin induces the growth of mammary tumors in syngeneic, and immunocompromised mice." (PMID 27999190, 2017). "Can we look at Leptin as a potential clinical biomarker for the development of breast cancer in subjects belonging to hereditary breast cancer families?" (PMID 29254161, 2017). "Collectively, these results substantiate the crucial role of ER signaling in leptin-induced growth of breast cancer cells." (PMID 29312618, 2017). "Effects of leptin on mammary tumor cell growth included several mechanisms such as up/down regulation of apoptosis, anti-apoptotic genes and modulation of the extracellular environment." (PMID 28930270, 2017). "Leptin upregulates the IL-1 system in endometrial cancer cells and the Notch pathway in breast cancer." (PMID 28659656, 2017). "Inhibition of estrogen receptor signaling via gene silencing or treatment with a pharmacological inhibitor (tamoxifen) abolished leptin-induced growth of MCF-7 human breast cancer cells." (PMID 29312618, 2017). "Leptin is thought to be involved in promoting breast cancer in obese women by stimulating the conversion of aromatizable androgens (androstenedione and dehydroepiandrosterone) to estradiol." (PMID 28983080, 2017).
breast cancer (continued). "In this study, we clearly demonstrated that ER signaling plays a crucial role in leptin-induced autophagy activation, which in turn facilitates the growth of breast cancer cells via both apoptosis inhibition and cell cycle progression." (PMID 29312618, 2017). "By measuring the changes in transcriptional regulatory regions of the p21WAF1/CIP1 promoter in the breast cancer cells, we observed the different effects of SAHA on regulation of p21WAF1/CIP1 expression in Leptin-induced breast cancer cells." (PMID 27926517, 2017). "Hence, Leptin may be an independent risk factor for breast cancer." (PMID 27926517, 2017). "About 40% of breast cancer cases showed leptin immunoreactivity in more than 50% of their transformed epithelial cells." (PMID 29121911, 2017). "To confirm that the breast cancer cells were responsive to leptin in our culture conditions, we measured cell proliferation as leptin has been shown to induce proliferation in a variety of cells." (PMID 28542577, 2017). "Inhibition of leptin signaling significantly reduces the establishment and growth of breast cancer and simultaneously decreases the levels of VEGF/VEGFR2, IL-1 and Notch." (PMID 28270795, 2017). "A validation of Leptin as a circulating biomarker of breast cancer development in larger series of HBCS subjects is needed." (PMID 29254161, 2017). "Herein, we demonstrated that ER signaling plays a crucial role in both leptin-induced cell cycle progression and apoptosis inhibition through autophagy induction in breast cancer cells." (PMID 29312618, 2017). "We analyzed blood plasma expression of leptin, adiponectin and ghrelin using Bio-Plex platform in 25 breast cancer patients with HBCS and in 38 healthy relatives." (PMID 29254161, 2017). "Low concentrations of Leptin (0.625 nM) significantly stimulated breast cancer cell growth, enhanced cell viability, minimized apoptosis, and increased cell cycle transition." (PMID 27926517, 2017). "Taken together, these results imply that ER signaling plays a critical role in leptin-induced activation of the AMPK/FoxO3A axis in MCF-7 breast cancer cells." (PMID 29312618, 2017). "In the present study, it was observed that, quercetin, curcumin and EGCG can exert significant protective effects against leptin-induced MCF-7 breast cancer cells after 48 h incubation period." (PMID 28930270, 2017). "Based on the results obtained from in vitro studies using ER-positive and ER–negative breast cancer cells, we demonstrated that ER signaling mediates leptin-induced growth of breast cancer cells via autophagy induction." (PMID 29312618, 2017). "Serum leptin is present in patients with breast cancer, and concentrations are higher in women with high-grade tumors." (PMID 28750624, 2017). "At the startup of Leptin treatment, the cell index curve changed irregularly, reflecting a stress reaction of the breast cancer cells." (PMID 27926517, 2017). "To elucidate the mechanisms how ER signaling mediates leptin-induced growth of breast cancer cells, we examined the role of ER signaling in leptin-induced cell cycle progression." (PMID 29312618, 2017). "In a similar study considering the effect of leptin on TAMs and breast cancer cells, the adipokine has been shown to induce IL-18 expression on both, eventually leading the breast cancer cells to invasion and metastasis." (PMID 28970834, 2017). "We also found that decreased circulating adiponectin levels and increased leptin, IL-6, IL-8, TNF-α, resistin and visfatin levels are significantly associated with risk of breast cancer." (PMID 29088874, 2017). "Leptin activated ER expression in ER-positive breast cancer cell line MCF-7 via the corresponding signal transduction pathway and up-regulated expression of ER-dependent genes." (PMID 27926517, 2017).
breast cancer (continued). "To elucidate the molecular mechanisms by which estrogen signaling mediates leptin-induced growth in breast cancer cells, we first confirmed the effect of leptin on the growth of breast cancer cells in our experimental conditions." (PMID 29312618, 2017). "Recently, two independent studies reported that LEP was among the most down-regulated genes in breast cancers of Lebanese and Saudi Arabian cohorts." (PMID 29268695, 2017). "Many studies have been performed to investigate the correlation of leptin (LEP) and leptin receptor (LEPR) polymorphisms with breast cancer (BC) risk, however the results are inconclusive." (PMID 28938640, 2017). "Leptin immunostaining is a useful method in supporting the diagnoses and prognoses of breast carcinoma." (PMID 29121911, 2017). "In the present work we have confirmed the Tyr-phosphorylation of Sam68 upon insulin and leptin stimulation in three different breast cancer cell lines." (PMID 27415018, 2016). "Leptin and both short and long OBR isoforms are overexpressed in breast cancer, especially in higher grade tumors and are associated with distant metastases." (PMID 26556856, 2016). "Leptin/ObRs are expressed at low levels in the epithelial cells of normal human mammary glands, but overexpressed in breast cancer cells." (PMID 27769315, 2016). "With the assessment of EMT-associated marker expression in MCF-7, SK-BR-3, and MDA-MB-468 cells, the effect of leptin on breast cancer cells was analyzed." (PMID 27769315, 2016). "Leptin significantly elevated the expression levels of Notch1-4, Notch target genes, Hey2 and increased survival in breast cancer cells; in addition, leptin is an inducer of Notch signaling through regulating Notch1-4 expression and/or activation." (PMID 27185268, 2016). "Tumor cells derived from MMTV-Wnt1 mice, a widely used model of mammary tumors, show decreased growth in ob/ob mice compared with cells from diet-induced obese mice that have functional leptin signaling." (PMID 26839577, 2016). "The leptin-ObR-IL-8 axis certainly adds another layer of complexity in the tumor microenvironment-breast cancer interaction, which drives cancer progression." (PMID 27588409, 2016). "Leptin levels and the expression of leptin receptor (ObR) are substantially higher in breast cancer cells and tissues than in normal mammary epithelial cells and tissues." (PMID 27588409, 2016). "Leptin was then immunodepleted from CAF- and adipocyte-derived CM using a specific leptin antibody, and resulting media were tested for the ability to induce mammosphere formation in breast cancer cells." (PMID 26556856, 2016). "The leptin antagonists Aca-1 and Allo-aca inhibit leptin-stimulated proliferation in breast cancer cells, MCF-7 and MDA-MB-23." (PMID 27480179, 2016). "It was reported that a novel bidirectional crosstalk between IGF-I and leptin signaling occurs in breast cancer cells." (PMID 27472371, 2016). "In a study of 35 primary breast cancers, 75% of tumors expressed leptin and 80% of tumors expressed the leptin receptor." (PMID 27338371, 2016). "Another leptin antagonist LDFI (leptin binding site I) also inhibits leptin-stimulated proliferation of breast cancer cells, MCF-7 and SKBR-3." (PMID 27480179, 2016). "Our studies extended these previous findings by demonstrating a direct involvement of leptin in sustaining breast cancer stem cell behavior using both breast cancer cell lines and metastatic breast cancer patient-derived cells." (PMID 26556856, 2016). "Leptin is angiogenic during tumorigenesis and insulin is involved in type-2 diabetes-mediated mammary tumor progression in mice." (PMID 27028862, 2016). "The complete medium was replaced by 200 ng/mL leptin or 20% Ad-CM to mimic the breast cancer cell-adipocyte microenvironment." (PMID 27983683, 2016). "As an important paracrine mediator, the adipocyte-derived cytokine leptin, that we have recently demonstrated to be also secreted by CAFs, has been correlated with breast cancer occurrence." (PMID 26556856, 2016).